MIR219B (microRNA 219b)
Synonyms: hsa-mir-2964a; MIR2964A; hsa-mir-219b; mir-219b
Gene: MicroRNA gene on chromosome 9 (128,392,621 to 128,392,708, forward strand). Ensembl gene ENSG00000283335.
Gene Ontology:
Biological process: miRNA-mediated post-transcriptional gene silencing
Cellular component: RISC complex
Homologues: Orthologues: rat Mir2964 (98% identical), tropical clawed frog xtr-mir-219 (53% identical), Drosophila melanogaster mir-219 (49% identical). Paralogues in human: MIR219A2 (62% identical).